IL6 (interleukin 6)
Diseases named in the same sentence as IL6 in open-access papers (continued):
Sharing a sentence is not in itself a finding about the gene and the disease.
infection (continued). "A comparison of the host inflammatory response to infection revealed a two-fold decrease in IL-6 production in the kidneys of mice infected with the Δstp1 strain compared to kidneys of mice infected with the Δstk1 strain." (PMID 20552019, 2010). "In C57Bl/6 mice, an early significant IFN-γ response was evident along with increased IL-6 and IL-10, which then decreased to near control levels by day 15 post-infection." (PMID 20625554, 2010). "Transcript levels for various cytokines/chemokines (KC [CXCL1], MCP-1 [CCL2], MIP-1α, IFN-γ, IL-4, IL-5, IL-6 and IL-10) were determined in lungs of infected mice on days 1, 6 and 9 post-infection." (PMID 20661429, 2010). "As enhanced immunity in this model is also associated with a decrease in pro-inflammatory cytokines, the levels of TNF-α and IL-6 were assessed in T. muris E/S restimulated MLNC culture supernatants during infection." (PMID 19950176, 2010). "Circulating levels of IFN-γ, TNF-α, IL-6, and IL-8 were assessed by ELISA and secondary infections were defined by IgM to IgG ratio." (PMID 20090849, 2010). "In contrast, the pro-inflammatory cytokines, TNF-α, IFN-γ, IL-1β, IL-6 and IL-12p70 only became detectable in the blood at 12 h post-infection and peaked by 72 h." (PMID 21124939, 2010). "By day 4 of infection, levels of IL-6 (180–345-fold), KC (28–98-fold), MCP-1 (35–280-fold), and RANTES (2–9-fold) were significantly above background in all challenge groups." (PMID 20967278, 2010). "Increase in body temperature is a systemic response to infection or inflammation and it is known to be mediated by endogenous pyrogens, including TNFα and IL-6." (PMID 20463923, 2010). "Infection of macrophages with Mtb-Δeis increased the production of tumor necrosis factor-α and interleukin-6 over the levels produced by infection with wild-type or complemented strains." (PMID 21187903, 2010). "First, we examined the daily regulation of cytokines mobilized following insult to the host by injury or infection, including TNFά, IL-1β, IL-6 and IL-18." (PMID 21194436, 2010). "In H5N1/2004 and H9N2/1997 infections, IL-6 was induced to a high level at 24 hours post-infection (4 and 3 folds, respectively); while H1N1/2002 induced a high level of IL-6 (about 8 folds) at 18 hours post-infection." (PMID 21108843, 2010). "Although no significant cytokine/chemokine induction was observed during the early phase of H1N1 infection; IP-10/CXCL-10, TNF-α, TGF-β2, CCL-5/RANTES, IL-8, and IL-6 were found to be 4-450 folds induced during the late phase of infection." (PMID 21108843, 2010). "TNFα protein levels increased steadily from day 2 through day 29 post-infection while IL6 and IFNγ protein levels peaked at day 9, before reducing to levels seen in mock infected animals." (PMID 20386712, 2010). "The inflammatory cytokines IFNγ and IL-6 are concomitantly produced in the lungs following infection as well." (PMID 20585449, 2010). "This rigorous approach has previously identified CD4+ T-cell counts, and serum IL-6 concentrations as independent predictors of infection." (PMID 20090932, 2010). "The mucosal innate immune response to infection was quantified in urine as the IL-6 and IL-8 concentrations and as neutrophil (PMN) numbers." (PMID 20505764, 2010). "In contrast, Il-1β, and Il-10 mRNA levels were not significantly different across strains, though the levels of Il-6 mRNA was markedly increased in MDA5−/− mice following infection." (PMID 20107606, 2010). "All cytokines/chemokines were equally expressed following infection with either of the two pH1N1 isolates, with the exception of increased expression of IL-6 and KC levels on day 1, following infection with the H274Y mutant virus." (PMID 20661429, 2010). "By day 7 of infection, levels of IFNγ (90–250-fold), IL-6 (360–390-fold), IL-17 (30–75-fold), KC (20–35-fold), TNFα (5–13-fold), and IL-2 (2–3.5 fold) were significantly elevated above background in all three vaccinated groups." (PMID 20967278, 2010).
infection (continued). "We report here that upon infection with live S. Typhi, human DC produced high levels of pro-inflammatory cytokines IL-6, IL-8 and TNF-α, but low levels of IL-12 p70 and IFN-γ." (PMID 19517022, 2009). "There were weak but significant correlations between the five markers of infection and the pro- and anti-inflammatory cytokines, interleukin-6 (IL-6), interleukin-8 (IL-8), interleukin-1Ra (IL-1Ra) and interleukin-10 (IL-10)." (PMID 19675669, 2009). "IL-6 and TNFα were previously known to play an important role in controlling the rapid dissemination of the bacteria upon infection." (PMID 19806192, 2009). "Pathways activated by IMI were IL-10 Signaling and IL-6 Signaling which likely reflected counter mechanisms of mammary tissue to respond to infection." (PMID 19925655, 2009). "The absence of TRAF6 resulted in enhanced viral replication and a significant reduction in the production of IL-6 and type I IFNs after infection with RNA virus." (PMID 19479062, 2009). "One of these, interleukin-6 (IL-6), is a major mediator of host response to tissue injury and infection." (PMID 20407653, 2009). "The serum levels of TNF-α, IL-1β and IL-6 augmented after challenge, reaching the maximum values between 24 h and 48 h post-infection." (PMID 19835595, 2009). "All other cytokine expressions were up regulated after SE challenge except that down regulated expression was observed at 1 h post-infection in IL-6." (PMID 21637513, 2009). "We report that CD37−/− mice are evidently better protected from infection than wild-type (WT) mice, which was accompanied by increased IL-6 levels and C. albicans–specific IgA antibodies." (PMID 19282981, 2009). "We observed that upon infection with live S. Typhi, human DC produced high levels of pro-inflammatory cytokines IL-6, IL-8 and TNF-α, but low levels of IL-12 p70 and IFN-γ." (PMID 19517022, 2009). "By 24 h post-infection, IL-6 gene expression in response to WT and ΔPT was 6- and 14-fold higher than that of the control group, respectively, suggesting an inhibitory role for PT on IL-6 gene expression early after infection." (PMID 19759900, 2009). "IL-6 expression levels were lowest among the four cytokines, and the peak expression levels occurred one and seven days post-infection." (PMID 19590756, 2009). "It has been demonstrated that the levels of expression of many cytokines, including TNFα, TNFγ, IL-6, IL-17 increase dramatically in intestinal lymphocytes during primary infection to E. tenella or E. acervulina." (PMID 19154572, 2009). "In patients with severe AP and in those patients with AP who developed infection, we observed low HLA-DR expression on monocytes and high serum IL-6 concentrations in samples taken at admission and one and three days later." (PMID 19442309, 2009). "IL-6 protein levels reflected the differences in gene expression in response to infection with WT and ΔPT." (PMID 19759900, 2009). "Here, we have demonstrated that levels of TNF and IL-6 and the transcription and DNA binding of NF-κB is significantly and differentially regulated by infection by two distinct MTb strains, HN878 or CDC1551." (PMID 19568431, 2009). "The aim of our present study was to measure the levels of TREM-1 and HLA-DR on monocytes, and the serum concentrations of IL-6 and IL-10 in patients with AP, and to determine whether these markers can be used for early identification of patients at high risk of developing severe AP or infection." (PMID 19442309, 2009). "Analysis of blood samples taken at 20 h post-infection and at termination showed that SR-A−/− animals had higher levels of bacteraemia and the pro-inflammatory cytokine, IL-6." (PMID 19214213, 2009). "INF-γ, IL-1, TNF-α and IL-6 are also instrumental in mounting an effective inflammatory response against infection." (PMID 19401694, 2009). "Treatment with L casei induced a stronger increase in IL-6, with values higher than those in the control group until 48 h post-infection." (PMID 19835595, 2009).
infection (continued). "Based on data suggesting that IL-6 is important in Treg induction and function, we monitored changes in Treg cell populations over the course of infection." (PMID 19587788, 2009). "These genes, along with Il6, were also the most upregulated in virulent strain infection, with expression levels at least 10-fold higher than those of mice infected with the attenuated strain." (PMID 19845042, 2009). "The concentrations of IFN-γ and IL-6, both highly produced by lymphocytes, began increasing in the lungs of adult mice at day 5 post-infection and 2-3 days later in aged mice." (PMID 19922665, 2009). "In our studies, there was significantly greater induction of IL-6 gene expression in response to ΔPT than WT on day 1 post-infection." (PMID 19759900, 2009). "The elevated IL-6 concentrations at 24 h after infection in CP-treated (CP+P-B+) mice (4427 pg/ml versus 80 pg/ml in control CP-P-B+ mice) were significantly lowered (P = 0.0064) upon phage application (593 pg/ml)." (PMID 19686585, 2009). "On the other hand, BALB/c primary lung epithelial cells produced a time-dependent increase in IL-6 only at 6 h and 24 h after which a decline in the IL-6 production was noted at 48 h post infection." (PMID 19806192, 2009). "Immune response-associated genes, with altered expression in virulent strain infection, were selected for further investigation: Tlr2, Tlr4, Tlr13, Myd88, Il1b, Il6, dectin-2 and Cxcl12." (PMID 19845042, 2009). "Our results suggest that IL-6 functions by regulating the balance of cytokines and chemokines during the early host response to infection." (PMID 19587788, 2009). "IL-6 is a cytokine that is rapidly produced at local tissue sites after disruption of homeostasis due to trauma or infection." (PMID 18769647, 2008). "The presence of CD8+ T cells in the lungs of both WT and IL-6−/− mice was also measured during days 2–12 of a primary and secondary infection with influenza virus." (PMID 18389078, 2008). "In order to evaluate the association between microbial DNA and intra-amniotic inflammation, results from end-point PCR and culture were correlated with amniotic fluid WBC count and IL-6 concentration, which typically are elevated in the setting of infection." (PMID 18725970, 2008). "As an illustrative example shown in this study, IBV-infection of Vero cells induces a drastic increase of IL-6 mRNA transcription at 8–24 hours post-infection." (PMID 18231581, 2008). "Our findings are supported by a previous study demonstrating elevated IL-6 production in the fallopian tubes of macaques after repeated infection with C. trachomatis." (PMID 18628987, 2008). "The serum levels of IL-6, a measure of systemic inflammatory response, were analyzed at day 7–8 of infection." (PMID 18493318, 2008). "The expression of IL-6 at the translational level was then analyzed by collecting the culture media and total infected cells at 24 hours post-infection by Western blot." (PMID 18231581, 2008). "The infected mice secreted significant amount of proinflammatory cytokines like TNFα and MCP-1 and high amount of IFNγ, IL-1 and IL-6 at 24 h post infection." (PMID 18937835, 2008). "A similar CD8+ T cell response was observed in the lungs of WT and IL-6−/− mice during the primary infection and following rechallenge with the same virus." (PMID 18389078, 2008). "Gene expression analysis provided evidence that expression levels of several immune response genes, including IFN-γ and IL-6, are high after pYV+ infection but low after sublethal ΔyopH infection." (PMID 18803824, 2008). "CRP is synthesized by the liver, mainly in response to IL-6, which is produced not only during infection but also in many types of inflammation." (PMID 19578505, 2008). "Since IL-6 is abundant following infection with influenza virus, we analyzed virus-specific T cell activity in both wild type and IL-6 deficient mice." (PMID 18389078, 2008).
infection (continued). "Transcription of il6, tnf, il10, mip2, and kc was strongly upregulated upon infection in the presence of XIAP, while induction of ifnb, il1b, ido, and inos was not significantly altered." (PMID 18769721, 2008). "RANTES, CC-CKR-3, TLR6 and IL-6 were highly up-regulated in Jurkat and K562 cells upon infection with dengue virus." (PMID 19117515, 2008). "The infection-induced accumulation of IL-6 and IFN-γ would be predicted by their respective mRNA abundance, whereas the accumulation of IL-10 was unexpected." (PMID 18575603, 2008). "Elevated levels of TNF-α and IL-6 were observed on day 3 post-infection, and rose dramatically along with IFN-γ and IL-12 on day 5, coincident with the increase in bacterial load in the spleen." (PMID 18483548, 2008). "In contrast, a similar bacterial burden was found in IFN-γR-/- and IL-6-/- mice compared to wild type mice after infection with ΔyopH." (PMID 18803824, 2008). "From earlier studies, it is known that IFN-γ and IL-6 are crucial for clearance of Ye wild type infection." (PMID 18803824, 2008). "To address this question we compared virus-specific CD4+ T cell responses in WT and IL-6−/− mice approximately three months after infection with influenza virus." (PMID 18389078, 2008). "Levels of all studied inflammatory markers (HMGB1, LBP, PCT, IL-6) and infection markers (C-reactive protein, white blood cell count, neutrophils) were elevated among bacteraemic patients." (PMID 17625012, 2007). "The concentrations of someproinflammatory cytokines, especially TNF-α, IL-6, and IL-8, in systemic circulationwere reported to increase in severe infections and septic shock." (PMID 18274637, 2007). "Este estudo investigou a eficácia do escore NNIS (National Nosocomial Infection Surveil-lance score), interleucina-6 (IL-6) e proteínas de fase aguda na predição de infecções pós-operatórias." (PMID 17505683, 2007). "Cytokines such as IL-1, TNF and IL-6 are key regulators of inflammation at sites of infection or tissue damage." (PMID 17328808, 2007). "In the early postoperative period, IL-6 and most of the acute-phase proteins were correlated with postoperative infection by means of univariate analysis." (PMID 17505683, 2007). "We have previously shown that C-reactive protein (CRP) and IL-6 were better markers for infection than soluble haemoglobin scavenger receptor (sCD163) in a population of patients prospectively admitted to a department of internal medicine." (PMID 17346334, 2007). "It is possible that the secretion of IL-1β, IL-6, IL-10, and TNFα in the choriodecidua region after infection with Escherichia coli would favor their trans-membranal translocation to the amnion and thereby exert their effect on the whole membrane." (PMID 18078521, 2007). "Transcripts encoding the proinflammatory cytokines IL-1β, IL-6, IL-8, and tumor necrosis factor (TNF)-α were markedly increased in late-stage animals (average fold increase at day 5 after infection: IL-1β, 3.9; IL-6, 4.3; IL-8, 11.3; and TNF-α, 5.2)." (PMID 17725815, 2007). "We investigated the efficacy of the National Nosocomial Infection Surveillance (NNIS) score, interleukin-6 (IL-6) and various acute-phase proteins for predicting postoperative infections." (PMID 17505683, 2007). "Infection occurred around 8 to 20 times more frequently in patients with IL-6 higher than 101 pg/ml on the second postoperative day or higher than 26 pg/ml on the fifth postoperative day, respectively." (PMID 17505683, 2007). "Significant increase of IL8 and IL6 mRNA after infection with A. pleuropneumoniae has previously been observed in lung lavage as well as lung tissue by northern blotting and in situ hybridisation." (PMID 17466061, 2007). "Infection with B.anthracis resulted in marked upregulation of IL-6, IL-10 and IL-12 in BALF 24 hrs after infection compared to saline treated controls." (PMID 17710136, 2007).
infection (continued). "The plasma concentration of IL-6 has alsobeen reported to correlate with severity of infection in certainclinical pathologic conditions." (PMID 17497030, 2007). "With these cut off levels CRP and IL-6 have sensitivities higher than 58% and specificities greater than 88% in diagnosing infection." (PMID 16569262, 2006). "Independently of productive infection, both IL-6 and IL-8 protein release were observed in the HASM cells derived from asthmatic donors." (PMID 16670028, 2006). "We have previously shown that CRP and IL-6 are better markers of infection and severity of infection than soluble hemoglobin scavenger receptor (sCD163) in a population of patients admitted to a Department of Internal Medicine." (PMID 16569262, 2006). "Using a cut off level of 16.3 pg/ml, IL-6 had a sensitivity of 79.2% and a specificity of 64.2% in diagnosing infection." (PMID 16569262, 2006). "• In a cohort of patients with less severe community-acquired infections, CRP, IL-6 and LBP appear to be superior to PCT as diagnostic markers for infection." (PMID 16569262, 2006). "Interleukin-6 (IL-6) is a proinflammatory cytokine that plays an important role in the host response to infection." (PMID 16611358, 2006). "Cytokines up-regulated from 3 hr post-infection onwards included IP-10, interferon beta and IL-6 whereas RANTES mRNA was only up-regulated at 6 hr post-infection." (PMID 16283933, 2005). "Infection of mouse fibroblast cells by HSV induces expression of IL-6, and infection of macrophages by HSV induces RANTES expression directly." (PMID 15507126, 2004). "Amniotic fluid was analyzed for the presence of microorganisms andendotoxin to confirm intraamniotic infection; cytokines interleukin (IL)-1β, IL-6, and IL-8 werealso assayed." (PMID 18475321, 1993). "Indeed, we found that repetitive RV16 infections led to reduced IL6 gene methylation in airway epithelial cells, which resulted in increased IL6 expression, release and subsequently activated an IL6TS." (PMID 41099307, 2026). "IL-6 is necessary for liver regeneration, and other reparative processes, indicating that complete inhibition of IL-6 signaling could impair recovery from injury or infection illustrating that both too little and too much IL-6 could be harmful." (PMID 41543641, 2026). "pylori infection-induced increase of cytokines (IL-6, IL-1β) in GES-1 cells." (PMID 42112454, 2026). "Basic Protocol 2 details a primary, human co-culture system that consists of SARS-CoV-2-infected primary human airway epithelia (HAE) grown at an air-liquid interface (ALI) and primary human PBMCs, and how to observe IL-1β and IL-6 crosstalk between these cell populations during infection." (PMID 41949496, 2026). "Analysis of differentially expressed genes in the LC group compared with the CC group at day 90–180 after infection identified an increase of multiple proinflammatory markers, such as IL6, NLRP3, TNF, JAK2, CSF2, IL1B and IL10, in the LC compared with the CC group." (PMID 41388153, 2026). "Recombinant MHV A59-7a infections elicited IL-6 and IL-12 production in BMDMs." (PMID 41400356, 2026). "Interestingly, we observed that p62-depleted macrophages had significantly more IL-6 gene expression compared with control cells at 24 h post-infection." (PMID 41583695, 2026). "IL-6, IL-4, and CRP may work as risk indicators of developing joint pain and chronic arthritis after the infection’s acute phase." (PMID 41598488, 2026). "If the concentration of IL-6 decreases to 50 pg/ml after 72 h but CD4+ T cell counts remain below 300/μl, tocilizumab should be discontinued and replaced with rIL-7 to mitigate the risk of secondary infections." (PMID 41521316, 2026). "The levels of IL6 increase as a first responder to the innate cell immune response to infection." (PMID 41598258, 2026).